EGR1 (early growth response 1)
Diseases named in the same sentence as EGR1 in open-access papers (continued):
Sharing a sentence is not in itself a finding about the gene and the disease.
tumor (467 papers, 2005 to 2026). "Transcriptomic analyses of Egr1-deficient tumors suggested immune dysregulation, including heightened inflammation and potential markers of T cell exhaustion in the tumor microenvironment." (PMID 41705258, 2025). "EGR1 is associated with the initiation and progression of cancer via involvement in tumor cell proliferation, invasion, metastasis, and angiogenesis." (PMID 40361912, 2025). "SFT-like tumors showed significantly worse outcomes, suggesting that expression of an EGR1 gene signature underlies tumor aggressiveness and/or therapy resistance." (PMID 40875449, 2025). "Nevertheless, EGR1 expression is associated with histological grade, lymphatic metastasis, tumor size, and TNM stage in patients (p < 0.05)." (PMID 39866235, 2025). "Expression of EGR1 is associated with tumor suppression due to cell cycle arrest and apoptosis by modulating tumor suppressor pathways, including PTEN." (PMID 40859429, 2025). "Regulators associated with tumorigenesis and tumor progression, such as EGR1, FOSL, BATF, and HOXB3, were enriched in malignant clusters." (PMID 39872221, 2025). "Correlation analysis with tumor-associated fibroblasts showed that Egr1 + FibC1 and Scp2 + Fib-C2 were highly correlated with pan-iCAF-2 and pan-pCAF, respectively." (PMID 38753279, 2024). "Egr1 is significantly associated with human cancer and plays a role in the proliferation, apoptosis, migration, and invasion of cancer cells and in the tumor microenvironment." (PMID 37783676, 2023). "The expression levels of KLF12 and EGR1 are associated with poor prognosis of the tumor and serve as potential diagnostic markers and therapeutic targets." (PMID 37606530, 2023). "EGR1 encodes early growth response, critically participating in neovascularization, tumor angiogenesis, and growth, together with ATF3, which can influence the limbal epithelial cell proliferation." (PMID 36187094, 2022). "The genes highly enriched in cluster 0, 3, and 13 CD8+ T cells from LAIT‐treated tumours were associated with T cell activation such as Fos, Jun, Pcdc1, Egr1, and Dusp1 or type I IFN responses such as Ly6a, and Ifi27l2a." (PMID 35808806, 2022). "A group of cells (C5) that did not express EMT signatures, but highly expressed myofibroblast-associated genes such as TAGLN and EGR1 was identified in the tumor cell clusters analysis." (PMID 35087207, 2022). "The expression of EGR1 decreases or even disappears in a variety of human malignancies, and its expression level is associated with tumor sensitivity to chemotherapy." (PMID 34497759, 2021). "The findings above suggested that EGR1 was positively associated with the tumor size, TNM staging, and the serum expression of TBIL, AST, ALT and AFP in patients." (PMID 34409922, 2021). "EGR1 expression was negatively associated with tumor invasion, lymph node status, histological grade, and TNM stage." (PMID 34497759, 2021). "Low EGR1 expression was significantly associated with several clinicopathological parameters including male gender (p = 0.034), tumor size (p = 0.014), and lymph node metastasis (p = 0.009)." (PMID 33477921, 2021). "Association of immunohistochemical staining for EGR1 with the tumor clinic pathological characteristic." (PMID 34497759, 2021). "Apoptosis is a process of programmed cell death under physiological conditions, and EGR1 causes tumor cell apoptosis through a variety of mechanisms." (PMID 33842351, 2021). "miR-183 is overexpressed in colon cancer and represses EGR1, which encodes a transcription factor that acts as a tumor suppressor, to promote tumor cell migration." (PMID 32674274, 2020). "The inhibition of CSPG4 signaling diminished AKT and ERK activity, reduced tumor-associated inflammation, decreased the transcription of pro-mitogenic early growth response protein 1 (EGR1), and facilitated the execution of pro-apoptotic programs." (PMID 31779130, 2019).
tumor (continued). "In a study using cDNA microarray and chromatin immunoprecipitation (ChIP) assay to assess the genes associated with tumor angiogenesis, Egr1 is identified as a key player to mediate HGF-induced upregulation of vascular endothelial growth factor and IL-8." (PMID 29607419, 2017). "Strikingly, low EGR1 levels were significantly associated with poor tumor histology (well: 68.4% (13/19); moderate: 55.6% (5/9); poor: 90.0% (27/30)) (P = 0.040), but not with age, gender, or TNM stage." (PMID 27244890, 2016). "Collectively, these findings suggest that Egr-1 plays important roles in tumor-associated angiogenesis and tumor progression." (PMID 25502753, 2014). "In contrast, Egr-1 overexpression appeared to make tumour cells more susceptible to GD-induced necrosis." (PMID 23152075, 2013). "Expression of EGR1 is significantly reduced in a number of tumor cells, and loss of expression of it is closely associated with tumor formation in mammalian cells and tissues." (PMID 21283769, 2011). "Kaplan-Meier survival statistics showed that tumors with high percentages of Egr-1 positive tumor nuclei had a significantly higher risk of progression to stage T2-4 (log-rank test, P = 0.035)." (PMID 19878561, 2009). "Nevertheless, in our study, Egr-1 was still found associated with tumor stage, tumor grade and progression to invasive tumors." (PMID 19878561, 2009). "In order to suppress EGR- 1 gene expression, a DNAzyme, which caused a 3-fold decrease in tumor size in mice, was designed." (PMID 22649602, 2009). "Finally, we demonstrated that EGR1 loss suppressed malignant phenotypes in vitro and reduced xenograft tumor growth in vivo." (PMID 41356200, 2026). "Similarly, loss of EGR1, either specifically in mitochondria or at the cellular level, inhibits tumor growth both in vitro and in nude mice." (PMID 41356200, 2026). "We also observed significant upregulation of genes encoding components of the NFAT/AP-1 signaling pathway heterodimers Junb and Fos, as well as NFAT associated transcription factors Egr1 and Egr2, and Tox in both unstimulated and tumor stimulated A1R CAR T cells." (PMID 40610421, 2025). "For example, EGR1, a TF that binds to 27 genes in our network, 7 known to be associated with poor and 4 associated with good cancer prognosis, has a complex role in cancer with both tumor-suppressing and tumor-promoting activities." (PMID 39013578, 2024). "The AURKAD132A mutation blocks the expression of cleaved caspase 3 and EGR1, which leads to reduced therapeutic effects of paclitaxel on colony formation and malignant growth of tumor cells in vitro and in vivo using a murine xenograft model and cancer patients." (PMID 38994036, 2024). "Mechanistic studies showed that ZHX1-mediated tumor promotion might be partially associated with early growth response 1 (EGR1)." (PMID 36232466, 2022). "The following clinical analyses suggested that high EGR1 expression in patients was associated with increased tumor size and advanced TNM staging, and decreased liver function (reflected by increased expression of TBIL, AST and ALT) and LC severity (increased expression of AFP)." (PMID 34409922, 2021). "EGR1 has been linked to tumor suppression during cancer progression." (PMID 34615546, 2021). "Interestingly, we also observed higher levels of CD8+ T cells expressing markers associated with tumor-resident memory cells such as Cd103 and Egr1." (PMID 32641748, 2020). "Both expression and nuclear translocation of EGR1 were reduced in F4/80+ TAMs in Il6−/− tumours, suggesting that loss of nuclear EGR1 expression might be responsible for the reduction of FAP expression by TAMs in the absence of IL-6." (PMID 30054470, 2018).
tumor (continued). "Egr-1 plays a crucial role in tumor-associated angiogenesis." (PMID 25502753, 2014). "Therefore, rapid and transient Egr-1 gene expression is crucial for tumor-associated angiogenesis and tumor progression." (PMID 25502753, 2014). "The distinct types of stress caused by anti-tumor drugs might promote up-regulation of EGR1, although anti-tumor drugs exert different pathways." (PMID 21283769, 2011). "It has been implicated that egr-1 functions as a tumor-suppressor." (PMID 20591135, 2010). "To assess whether HCCR-1-induced tumor formation is associated with the loss of egr-1 expression, we tested the time course of egr-1 expression." (PMID 20591135, 2010). "Egr1 is a tumor suppressor gene that has been associated with suppression of proliferation." (PMID 20205934, 2010). "Furthermore, Kaplan-Meier survival analysis showed that a high frequency of tumor cells with nuclear Egr-1 immunolabelling was significantly associated with a higher risk of progression to stage T2-4 (log-rank test, P = 0.035)." (PMID 19878561, 2009). "Moreover, overexpression of EGR1 facilitated the anti-tumor effect caused by erastin in vivo." (PMID 39006084, 2024). "Thus, Snail, Dlx-2, and Egr-1 seem to be implicated in GD-induced necrosis and tumor progression." (PMID 29636841, 2018). "ex., typical tumor drivers BCAN, APOE, and EGFR or genes associated to neuronal function like EGR1, FOS, and MARCKS)." (PMID 40188875, 2026). "IGFBP7 suppresses tumor cell proliferation and migration by inhibiting the expression of EGR1, thereby downregulating the activity of the TGF-β1 signaling pathway." (PMID 41692778, 2026). "Transcriptomic profiling of 16 tumours was performed to investigate correlations between Hippo pathway and EGR1 transcriptional signatures." (PMID 41665771, 2026). "These Egr1+ neutrophils co-localize with reprogrammed hepatocytes at the tumor-liver interface, where they promote vascular remodeling to facilitate metastatic colonization." (PMID 41654488, 2026). "Western blot analysis of tumor tissues revealed decreased LC3B and increased p62 protein levels in EGR1 knockdown groups (Cas13a-gEGR1 and shEGR1), confirming that EGR1 regulates tumor growth via the mitophagy pathway." (PMID 41356200, 2026). "It should be noted that EGR1 has been reported to exhibit both tumor-suppressive and pro-oncogenic properties in HCC, a duality largely shaped by the cellular signaling context, including microenvironmental cues such as hypoxia." (PMID 41356200, 2026). "AM80 treatment significantly reduced the nuclear localization of ATF5 and induced EGR1 expression in the nuclei of tumor tissues." (PMID 40124511, 2025). "The subcutaneous tumor xenograft experiment performed with nude mice showed that tumors derived from cells with elevated EGR1 expression had a significantly reduced volume compared to those formed from control cells." (PMID 39866235, 2025). "Evidence from various malignancies shows that EGR1 can function as a tumor suppressor by monitoring DNA damage, promoting tumor cell apoptosis, and enhancing the effectiveness of radiotherapy and chemotherapy." (PMID 41155227, 2025). "Since ATF3 expression was very low in both APA tumor and adjacent tissues from the spatial transcriptome analysis, we selected EGR1 for further investigation." (PMID 39826326, 2025). "Depending on the kind of cancer, EGR1 has been shown to have both tumor-promoting and tumor-suppressive properties." (PMID 39866235, 2025). "Within tumours, EGR1 promotes metastasis and drug resistance by stimulating the generation of tumour stem cells." (PMID 40292733, 2025).
tumor (continued). "Our previous research has shown that basic leucine zipper ATF-like transcription factor (BATF) and early growth response 1 (EGR1) play a role in chimeric antigen receptor T (CAR-T) cell exhaustion during AML tumor elimination." (PMID 40225861, 2025). "In the univariate survival analysis, it was found that TNM stage, tumor size, histological grade, and EGR1 expression are factors influencing the prognosis of ccRCC patients (p < 0.05)." (PMID 39866235, 2025). "Conversely, in specific tumor microenvironments like hypoxia, elevated EGR1 expression supports tumor cell survival, proliferation, metastasis, and neoangiogenesis." (PMID 41155227, 2025). "For example, inflammatory cytokines downregulate EGR1 expression, leading to a significant reduction in LNCRTCTS, a tumor-suppressive lncRNA controlled by EGR1." (PMID 40823082, 2025). "In our previous research on CAR-T cell-mediated elimination of AML tumor cells, we found that BATF downregulation and EGR1 upregulation are closely associated with reduced CAR-T cell exhaustion and enhanced cell functionality." (PMID 40225861, 2025). "While several studies have shown that EGR1 can promote cell and tumor proliferation, our findings suggest a different role in the context of PA." (PMID 39826326, 2025). "In the context of PCa bone metastases, osteocyte-derived GDF15 promotes tumor growth by upregulating early growth response 1 (EGR1) expression through the GFRAL pathway." (PMID 40868185, 2025). "In contrast, RSPO3 derived from myCAFs can up-regulate EGR1 expression in tumor cells, promoting the conversion of gastric cancer cells into the MP7 state and thereby enhancing the tumor’s invasiveness and drug resistance." (PMID 41583453, 2025). "EGR1 mRNA levels were significantly downregulated in 20 APA tumor specimens compared with their paired adjacent adrenal cortex." (PMID 39826326, 2025). "The previously unrecognized neuroendocrine signature in SFTs and the startling number of neural genes activated via NAB2-STAT6/EGR1 elicits further questions about the identity of the tumor-initiating cells." (PMID 40875449, 2025). "The tumor tissues of nude mice co-treated with knockdown EGR1 and gemcitabine showed decreased tumor volume, decreased body weight, and lower proliferation capacity than the sh-NC group, enhancing the inhibitory effect of gemcitabine on tumor growth." (PMID 38408959, 2024). "The results from the xenograft models affirm the potential of targeting the WTAP/EGR1/PTEN axis as a strategic approach for inhibiting tumor progression and stem cell-driven tumor propagation in EC." (PMID 39044249, 2024). "In animal experiments, knockdown of EGR1 enhanced the inhibitory effect of gemcitabine on tumor growth compared with the sh-NC group." (PMID 38408959, 2024). "In the context of tumor cells, Egr1 plays a dual role, functioning as both a tumor suppressor gene and a tumor-promoting gene." (PMID 38672136, 2024). "This induces the expression of EGR1 target genes, which have a biological effect, ultimately forming a feed-forward loop that drives tumor progression." (PMID 39175476, 2024). "The expression of cleaved caspase 3 and EGR1 decreased in the AURKAD132A tumor tissues after Taxol treatment compared with the expression levels in the AURKAWT or vector groups." (PMID 38994036, 2024). "Following a period of twenty-one days, the analysis of tumor growth curve, tumor sizes, tumor weight and Ki67 staining demonstrated that EGR1 downregulation significantly stimulated tumor growth in the in vivo setting." (PMID 38287371, 2024). "We particularly observed relationships with SIGLEC + macrophages, LAM2 APOE + macrophages, and EGR1 + macrophages, which are analogous to M2-like, tumor-promoting, macrophages." (PMID 39529126, 2024).
tumor (continued). "In radiation-induced breast cancer stem cells, EGR1 remodels the tumor stroma to promote tumor metastasis by inducing protease connexin-1 (PN-1) upregulation." (PMID 38385088, 2024). "Compared with the control group, tumor metastases were significantly increased in models which GC cells were simultaneously inoculated with EGR1-overexpressing mesothelial cells." (PMID 38385088, 2024). "Early growth response 1 (EGR1) plays an important role in tumor cell proliferation, angiogenesis and invasion." (PMID 38385088, 2024). "Conversely, the tumor metastases were significantly reduced in EGR1-knockout mesothelial cells and GC cells inoculated group." (PMID 38385088, 2024). "The tumour suppressor markers early growth response 1 (EGR1) and dual specificity phosphatase 6 (DUSP6) were downregulated by ∼2-fold in the presence of a bone stroma compared to a fibroblast stroma (p < 0.005)." (PMID 38226014, 2024). "The loss of EGR1 and PTEN due to miR-183 upregulation contributes to increased tumor aggressiveness and a poorer prognosis." (PMID 39594601, 2024). "In certain cases, EGR1 (early growth response factor 1) has been shown to induce tumor cell apoptosis, whereas it promotes tumor proliferation and angiogenesis in hypoxic conditions." (PMID 39200696, 2024). "Bevacizumab-resistant tumor cell-derived FGFBP1 induced fibroblast activation protein α expression by enhancing the paracrine FGF2/FGFR1/ERK1/-2/EGR1 signaling pathway in hepatic stellate cells." (PMID 39668826, 2024). "In our immunohistochemical results, after knockdown of EGR1, Ki-67 positivity in animal tumor tissues was reduced compared with that in the sh-NC group, indicating that tumor proliferation and growth were slowed down." (PMID 38408959, 2024). "We analyzed the significantly upregulated genes in TDECs related to tumor growth factors and selected Angpt2, Lama4, Egr1, Egr3, and Vegfa." (PMID 39440923, 2024). "Despite the low expression of EGR1 in mesothelial cells under normal conditions, a significant increase in EGR1 can be observed under inflammatory and tumor conditions." (PMID 38385088, 2024). "EGR1's multifaceted role, functioning as an oncogene in some cancers and a tumor suppressor in others, highlights its therapeutic potential." (PMID 39120790, 2024). "The restoration of EGR1 in PD-L1-silenced cells rescues angiogenic and tumor growth capabilities, highlighting EGR1 as a key mediator in this pathway." (PMID 39421442, 2024). "It has been demonstrated that EGR1 can regulate angiogenesis to promote tumour cell invasion, which is upregulated in the EMT process and regulates the target gene HSPG2 to promote EMT." (PMID 37817210, 2023). "Experimental validation revealed that suppressing EGR1 expression inhibited tumour cell invasion, significantly upregulated the expression of E-cadherin and decreased the expression of N-cadherin." (PMID 37817210, 2023). "Egr-1, a gene that suppress tumor growth, and PTEN, a new oncogene whose expression stops unchecked cell growth, thereby preventing the development of tumors." (PMID 37546387, 2023). "Mechanistically, LINC-PINT interacts with PRC2 at a few tumor-invasion-related gene loci, such as Early Growth Response 1 (EGR1) and Integrin alpha 3 (ITGA3), and induces their silencing, ultimately repressing cancer cell migration." (PMID 36750826, 2023). "Egr-1 is believed to have a significant impact on tumor cell proliferation, invasion, metastasis, and angiogenesis." (PMID 37046823, 2023).